SLC16A3 (solute carrier family 16 member 3)
Description:
Proton-dependent transporter of monocarboxylates such as L-lactate and pyruvate. Plays a predominant role in L-lactate efflux from highly glycolytic cells (By similarity).
Synonyms: MCT 4; MCT3; MCT4; MCT 3; MCT-3; MCT-4
Tractability: Small molecule: a high-quality ligand is known. Antibody: UniProt places it where antibodies can reach, with high confidence; its Gene Ontology location is reachable by antibodies, with high confidence; UniProt predicts a signal peptide or a membrane-spanning region; the Human Protein Atlas places it where antibodies can reach. PROTAC: ubiquitination databases record sites on it; its protein half-life has been measured; a small molecule that binds it is known.
Target class: SLC16 family of monocarboxylate transporters; Electrochemical transporter; SLC superfamily of solute carriers; Transporter
Chemical probes: MSC-4381 (high quality)
Gene: Protein-coding gene on chromosome 17 (82,217,878 to 82,261,129, forward strand). Ensembl gene ENSG00000141526.
Subcellular location: Cell membrane; Basolateral cell membrane
Subcellular location (Human Protein Atlas): Plasma membrane; Nuclear membrane
Pathways (Reactome):
Hemostasis: Basigin interactions
Transport of small molecules: Proton-coupled monocarboxylate transport
Gene Ontology:
Molecular function: lactate:proton symporter activity; protein binding; pyruvate transmembrane transporter activity; RNA binding; monocarboxylic acid transmembrane transporter activity; lactate transmembrane transporter activity; transmembrane transporter activity
Biological process: lactate transmembrane transport; pyruvate transmembrane transport; monocarboxylic acid transport; plasma membrane lactate transport; pyruvate catabolic process; transmembrane transport
Cellular component: apical plasma membrane; basolateral plasma membrane; lateral plasma membrane; plasma membrane; membrane
Genetic constraint (gnomAD): Loss-of-function variants: 23 observed, 23.24 expected, observed/expected ratio (o/e) 0.99, 90% interval 0.71 to 1.4. The synonymous counts are far from expectation, so gnomAD's model fits this gene poorly and the ratio says little. Missense variants: 731 observed, 627.64 expected, observed/expected ratio (o/e) 1.16, 90% interval 1.1 to 1.24. Synonymous variants: 390 observed, 291.12 expected, observed/expected ratio (o/e) 1.34, 90% interval 1.23 to 1.46.
Homologues: Orthologues: chimpanzee SLC16A3 (98% identical), macaque SLC16A3 (98% identical), rat Slc16a3 (90% identical), mouse Slc16a3 (90% identical), dog SLC16A3 (88% identical), guinea pig SLC16A3 (88% identical), pig SLC16A3 (87% identical), tropical clawed frog slc16a3 (78% identical), rabbit SLC16A3 (76% identical), zebrafish slc16a3b (73% identical), zebrafish slc16a3a (72% identical), Drosophila melanogaster Mct1 (29% identical), and 12 more. Paralogues in human: SLC16A8 (58% identical), SLC16A1 (44% identical), SLC16A7 (44% identical), SLC16A5 (36% identical), SLC16A12 (33% identical), SLC16A11 (30% identical), SLC16A6 (30% identical), SLC16A13 (27% identical), SLC16A14 (26% identical), SLC16A9 (26% identical), SLC16A10 (26% identical), SLC16A2 (24% identical), and 1 more.
Diseases named in the same sentence as SLC16A3 in open-access papers:
SLC16A3 is named in the same sentence as 66 diseases in open-access papers, as found by Europe PMC text mining. Sharing a sentence is not in itself a finding about the gene and the disease. The quoted sentences say what the papers report.
breast carcinoma (14 papers, 2012 to 2025). "The investigation revealed that mutations in SLC16A3 were most prevalent in hepatobiliary cancer (> 5%), followed by endometrial cancer, pleural mesothelioma, breast cancer, and ovarian Epithelial tumor (> 4%)." (PMID 40301866, 2025). "Notably, previous study has linked the lactate transporter SLC16A3 to the tumour immune microenvironment, particularly in breast cancer." (PMID 39656344, 2024). "Meanwhile, MCT4 (SLC16A3) was upregulated in breast cancer tissue in IHC analysis, particularly TNBC subtypes, and associated with high tumour grade and poor prognosis." (PMID 41154605, 2025). "It was found that the SLC16A3 gene alteration rate is highest (> 4%) in hepatobiliary cancer, endometrial cancer, pleural mesothelioma, breast cancer, and ovarian epithelial tumor, Amplification, miss mutation, and deep deletion are the main." (PMID 40301866, 2025). "The observation regarding SLC16A3 is notable because high expression worsens (or tends to worsen) patient prognosis in the other breast cancer molecular subtypes." (PMID 34219652, 2021). "Additionally, SLC16A3 has been discovered to inhibit the inflammatory polarization of macrophages in breast cancer." (PMID 38779008, 2024). "Indeed, knock-down of SLC16A3 expression in breast cancer cells reduces the capacity of pHi to recover from an acid load." (PMID 37999800, 2024). "Analyzing all tumor subtypes together suggested that the alterations in expression of glycolytic (SLC16A3)- and mitochondrial (GFM2)-associated genes may be a general feature of aggressive breast cancers." (PMID 37608351, 2023). "Interestingly, both ALDOA and SLC16A3 are also suggested to be hypoxia responsive and is upregulated in hypoxic breast cancer with poor outcome." (PMID 23216862, 2012). "“Expression of SLC16A3 gene is higher in breast cancer distant metastasis....”." (PMID 23216862, 2012). "SLC16A3 (MCT4) has been shown to regulate cell migration and invasion, particularly in breast cancer cell lines, by interacting with β1 integrin and altering focal adhesion." (PMID 40362545, 2025). "In contrast, SLC16A3 mRNA expression was high and SLC16A1 mRNA expression very low in luminal B breast cancer tissue." (PMID 34219652, 2021). "Butyrate induced the transcription of SLC16A3, SLC26A3, and HIF1A in sheep ruminal epithelia, human breast cancer, and colon cell lines." (PMID 30258628, 2018). "However, LEC gene expression data of MCF-7 cc and SK-BR-3 cc suggested import and export of lactate between breast cancer cells and LECs could occur at similar rates since SLC16A1 and SLC16A3 expression were similar." (PMID 33277521, 2020).
lung adenocarcinoma (10 papers, 2020 to 2026). A carcinoma that arises from the lung and is characterized by the presence of malignant glandular epithelial cells. "Given that cisplatin is a first-line chemotherapeutic agent for lung adenocarcinoma, we further investigated the relationship between the risk gene SLC16A3 and cisplatin sensitivity." (PMID 41583466, 2025). "Other studies have shown that SLC16A3 is highly expressed in lung adenocarcinoma tissues and is associated with poor prognosis in patients." (PMID 39275122, 2024). "Our previous study also revealed that SLC16A3 is highly expressed in lung adenocarcinoma and is associated with poor prognosis and immune cell infiltration." (PMID 35401672, 2022). "SLC16A3 is associated with pancreatic cancer and glioblastoma and can predict tumor metastasis and survival in lung adenocarcinoma." (PMID 33613623, 2020). "Analysis of the GSE213102 and GSE222187 datasets revealed that SLC16A3 expression was significantly lower in multiple cisplatin-resistant lung adenocarcinoma cell lines compared to their corresponding parental cells." (PMID 41583466, 2025). "Analysis of public datasets revealed that SLC16A3 expression is higher in cisplatin-sensitive lung adenocarcinoma cells." (PMID 41583466, 2025). "Our in vitro experiments indicate the involvement of SLC16A3 in the malignant phenotype of lung adenocarcinoma cells." (PMID 38779008, 2024). "Similarly, in the GSE108214 dataset, SLC16A3 expression was also higher in cisplatin-sensitive lung adenocarcinoma cell lines." (PMID 41583466, 2025). "Moreover, knocking down SLC16A3 in lung adenocarcinoma cells attenuated cisplatin-induced apoptosis." (PMID 41583466, 2025). "To investigate their biological functions, we separately performed SLC16A3 knockdown and EGR2 overexpression in lung adenocarcinoma cells, with transfection efficiency confirmed by Western blotting." (PMID 41583466, 2025). "As the functional roles of the two representative signature genes SLC16A3 and EGR2 in lung adenocarcinoma progression remain incompletely elucidated, we selected them for expression and functional validation using a series of in vitro assays." (PMID 41583466, 2025).
melanoma (9 papers, 2005 to 2025). A malignant, usually aggressive tumor composed of atypical, neoplastic melanocytes. "The MCT4 (SLC16A3) protein catalyzes the proton-linked bidirectional transport of monocarboxylates, such as lactate, pyruvate, and ketone bodies, across the cell membrane, and its elevated expression is associated with progression to advanced melanomas." (PMID 30795533, 2019). "Levels of aberrant N6−methylation of adenosine (m6A) at SLC16A3 were also relevant to the efficacy of immunotherapy in melanoma." (PMID 36768316, 2023). "Another study suggested that elimination of ALKBH5 (RNA m6R demethylase) reduced the expression of MCT4/SLC16a3 on melanoma cells, reduced the accumulation of lactic acid in TME, and weakened the immunosuppressive function of Tregs." (PMID 36387147, 2022). "Knockdown of Alkbh5 in melanoma and colon cancer cells resulted in m6A-dependent decreases in the stability of Mct4/Slc16a3 mRNA, a regulator of lactate secretion." (PMID 35350378, 2022). "Coherently, in silico analysis of a TCGA melanoma dataset (n = 448 patients) revealed that the expression of LDH‐A, HK2 (encoding gene for HKII) and SLC16A3 (encoding gene for the transporter MCT4) inversely correlate with oestrogen‐related receptor alpha (ERRα), a representative female sex marker." (PMID 39888245, 2025). "ALKBH5 plays an immunomodulatory role in melanoma, colorectal cancer and other tumors, not only regulating Mct4/Slc16a3 molecules related to tumor survival, metastasis and metabolism, but also affecting the number of tumor-infiltrating Treg cells and bone marrow derived inhibitory cells (MDSC)." (PMID 36618420, 2022). "The m6A demethylase Alkbh5 has effects on m6A density and splicing events in tumors during ICB therapy and modulates MDSCs accumulation in TME by regulating Mct4/Slc16a3 expression and lactate content of the TME in the employed melanoma and colon syngeneic mouse models." (PMID 37006306, 2023). "Several genes not previously known to be upregulated by hypoxia included Ribonuclease 4 RNAse4 3.1-fold, monocarboxylate transporter family member 4 (SLC16A3 also called MCT4), Preferentially expressed antigen of melanoma PRAME 4.9-fold and Importin Beta 3 4.1-fold." (PMID 16052224, 2005).
ovarian carcinoma (7 papers, 2020 to 2025). A malignant neoplasm originating from the surface ovarian epithelium. "Although SLC16A3 was found to be associated with poor patient outcomes in ovarian cancer, several studies have indicated the same trend for both SLC16A1 (MCT1) and SLC16A3 (MCT4) in different cancers." (PMID 37934721, 2023). "SLC16A3 demonstrated a greater association with oncogenic properties and was validated in ovarian cancer cell lines." (PMID 37934721, 2023). "Overall, this suggests the potential role of increased SLC16A3 expression levels in reducing the life expectancy of Ovarian cancer patients." (PMID 37934721, 2023). "When the GeneChip dataset in TNMplot was compared, SLC16A3 was found to increase significantly in the tumor and metastatic tissues in Ovarian cancer samples as compared to normal tissues, while other members showed a significant decrease in metastatic tissues." (PMID 37934721, 2023). "Results indicated that high SLC16A3 and PFKP expression in patients with advanced ovarian cancer was associated with poor PFS, and high SLC16A3 expression in patients with poor or moderate differentiation was associated with poor PFS or PPS." (PMID 34277429, 2021). "Kaplan-Meier plotter analysis indicated that among the highly expressed glycolysis genes, SLC16A3, HK2, GPI, PFKP, and PGK1, were closely associated with poor PFS, PPS, or OS in patients with ovarian cancer." (PMID 34277429, 2021). "SLC16A3, PFKP, and PGK1, which were highly expressed in ovarian cancer tissues in two databases and associated with poor prognosis, were selected for further analysis." (PMID 34277429, 2021). "CEBPB could also promote the transcription of SLC16A3 to help the progression of ovarian cancer." (PMID 38007473, 2023). "Compared to normal tissues, ovarian cancer tissues showed higher mRNA levels for SLC16A1 and SLC16A3, the two most important lactate transporters." (PMID 37934721, 2023). "For instance, SLC16A3, mediated by LINC00035/CCAAT enhancer binding protein beta (CEBPB), enhanced the glycolysis and promoted the development of ovarian cancer." (PMID 36768316, 2023). "SLC16A3, more than SLC16A1, shows a significant increase in female reproductive cancer (breast 21:0, cervical 4:1 and ovarian cancer 7:0)." (PMID 32355273, 2020). "As shown in the UALCAN dataset, the SLC16A3 protein was highly expressed in BRCA, ccRCC, COAD, GBM, HCC, HNSC, LUAD, PAAD, and UCEC, but was lower in gastric cancer and did not significantly differ in ovarian cancer." (PMID 40301866, 2025).
pancreatic cancer (7 papers, 2020 to 2025). "However, more research attention should be paid to the association between SLC16A1, SLC16A3 and pancreatic cancer as new indicators in large patient cohorts." (PMID 32355273, 2020). "It was reported that the overexpression of SLC16A3 is correlated with prognosis in pancreatic cancer." (PMID 35991839, 2022). "Low expression of SLC16A3 in patients with pancreatic cancer indicated a better survival time (HR = 1.7, log-rank P-value = 0.011)." (PMID 32355273, 2020). "The studies from the Oncomine database also clearly show the differences in increasing levels of SLC16A1 and SLC16A3 between pancreatic cancer and normal tissue." (PMID 32355273, 2020). "SLC16A3 has been shown to be a possible biomarker for prognosis of pancreatic cancer." (PMID 33903282, 2021). "These significantly enriched GO terms and KEGG pathways could help us deeply understand the function of SLC16A1 and SLC16A3, which are involved in the occurrence and progression of pancreatic cancer." (PMID 32355273, 2020). "Taken together, our findings, including the IHC pattern, demonstrated that SLC16A1 and SLC16A3 could be potentially ideal prognosis makers and therapy targets for patients with pancreatic cancer as treatment strategies." (PMID 32355273, 2020). "SLC16A3 had a major effect on the metabolic process of pancreatic cancer." (PMID 32355273, 2020). "The boxplot of the RNA-Seq expression in 179 pancreatic cancer vs 171 normal pancreas samples demonstrated that SLC16A1, SLC16A2, SLC16A3, SLC16A4, SLC16A5 and SLC16A13 were increased with statistical meaning." (PMID 32355273, 2020). "One gene, SLC2A1, is present in five tumor entities (renal, urothelial, lung, liver and pancreatic cancer) and PLS3, SLC16a1, and SLC16A3 are present in four tumor entities." (PMID 32599841, 2020). "SLC16A1, SLC16A3 and SLC16A13 exhibited biomarker potential for prognosis, and we further identified their related genes and regulatory networks, revealing core molecular pathways that require further investigation for pancreatic cancer." (PMID 32355273, 2020). "However, in our selected validation cohort (GSE28735), which contains 45 pancreatic cancer patients with overall survival time, we observed that SLC16A1 and SLC16A3 only demonstrate the same trend if separated the patients into high and low groups at median expression." (PMID 32355273, 2020).
glioblastoma (6 papers, 2015 to 2021). The most malignant astrocytic tumor (WHO grade IV). "Furthermore, the monocarboxylate transporters 1 and 4 (MCT1 and MCT4, encoded by SLC16A1 and SLC16A3, respectively) that are typically overexpressed in glioblastomas, are underexpressed or silenced in glioblastomas that possess IDH1 mutations." (PMID 33019704, 2020). "Our findings are also in agreement with a previous study showing that SLC16A3 (MCT4) mRNA levels were lower in patient-derived mutant IDH1 models compared to wild-type IDH1 glioblastoma models." (PMID 27144334, 2016). "In view of lactate accumulation upon PDHC inhibition, the ability of cancer cells to extrude lactate faster through higher expression of SLC16A8, aided by SLC16A3 in U87 cells, may also contribute to the higher resistance to the P-analogs of the glioblastoma vs HEK293 cell lines." (PMID 26503465, 2015).
glioma (6 papers, 2021 to 2025). A benign or malignant brain and spinal cord tumor that arises from glial cells (astrocytes, oligodendrocytes, ependymal cells). "MCT4/SLC16A3 has been shown to be overexpressed in many malignant tumors including gliomas under hypoxic conditions within the tumor center." (PMID 33936203, 2021). "In summary, our data highlight MCT4/SLC16A3 as a key gene for distinct hallmarks of tumor malignancy in glioma cells." (PMID 33936203, 2021). "In a nutshell, our study provides broad functional evidence for MCT4/SLC16A3 as a key driver for multiple hallmarks of malignancy in glioma." (PMID 33936203, 2021). "A previous study reported that glioma cells with IDH1 mutation produce 2-hydroxyglutarate, which promotes HIF-1α degradation, accompanied by the downregulation of glycolysis-related genes including SLC2A1, PDK1, LDHA, and SLC16A3." (PMID 33627136, 2021). "Hypoxic wt-IDH glioma tissues from patients show a glycolytic phenotype due to the upregulation of PGK1, PKM2, LDHA, SLC16A3, and CA9 via HIF1." (PMID 38786726, 2024). "Meanwhile, the glioma patients with higher PTBP1, SLC39A1, MMP9, and SLC16A3 expression had shorter OS (p < 0.01)." (PMID 36307882, 2022). "The expression levels of EMB, LDHA, SLC16A1, SLC16A3, SLC16A8, PARK7, and PFKFB2 were lower in 1p/19q Codel glioma than those in non-Codel glioma." (PMID 36698888, 2022).
lung carcinoma (5 papers, 2019 to 2025). "It was recently shown that the presence of TMPRSS11B (also named HATL5) in the BSG-SLC16A3 complex increases the rate of SLC16A3-driven lactate export in lung cancer cells." (PMID 40508207, 2025). "Notably, the proteolytic cleavage of BSG by the sheddase TMPRSS11B was shown to enforce lactate export by SLC16A3 in lung cancer." (PMID 40508207, 2025). "SLC16A3 predicts a worse prognosis in lung cancer and may involve in immune microenvironment in lung cancer." (PMID 38957564, 2024). "Within the chamber without matrix gel, the migratory capacity of lung cancer cell lines with downregulated SLC16A3 was significantly reduced." (PMID 38779008, 2024).
hepatocellular carcinoma (4 papers, 2022 to 2025). A malignant tumor that arises from hepatocytes. "Previous research demonstrated that elevated levels of MCT4 (SLC16A3) can contribute to immunosuppression in hepatocellular carcinoma." (PMID 40301866, 2025). "Prior research has demonstrated the prognostic potential of SLC16A3 in hepatocellular carcinoma, cholangiocarcinoma, and bladder cancer." (PMID 38779008, 2024). "We established a subcutaneous tumour model of mouse hepatocellular carcinoma (HCC) and utilised an SLC16A3 inhibitor (MCT4i) to investigate the role of SLC16A3 in HCC progression." (PMID 39656344, 2024).